KRT17 (keratin 17)
Diseases named in the same sentence as KRT17 in open-access papers (continued):
Sharing a sentence is not in itself a finding about the gene and the disease.
tumor (continued). "Altogether, we found KRT17 positivity in 77% papillary RCTs irrespectively of the size of tumor cells such as small, medium or large cell which are considered by others as type I and type II or mixed type." (PMID 31602265, 2019). "We found a positive staining in ureteric bud and collecting duct cells in foetal kidney, in all papillary preneoplastic lesions and also in 77% of the 151 papillary renal cell tumors indicating a continuos KRT17 expression during tumor development." (PMID 31602265, 2019). "In this Cohort 94 tumors (14%) displayed positive KRT17 staining which showed a significant correlation with cancer specific death, tumor size, T-stadium, grade and stage." (PMID 31602265, 2019). "The clinical, pathological as well as experimental data strongly suggest the involvement of KRT17 neo-expression in tumor progression." (PMID 31602265, 2019). "The neo-expression of KRT17 in these cases showed a significant correlation with tumor progression and metastasis." (PMID 31602265, 2019). "Keratin 17 was indeed found frequently overexpressed also in LUAD, thus questioning its diagnostic role in distinguishing between the two tumor types." (PMID 30473748, 2018). "The variation in expression of the 25 MIBC marker genes plus p63 and KRT17 was determined for the tumor transplants generated from the six independent isolates of the As3+ and seven independent isolates of the Cd2+ -transformed UROtsa cells." (PMID 30550540, 2018). "KRT1, KRT6, KRT16 and KRT17 showed strong staining in the well-differentiated cells in the center of the tumor nests when compared to the staining in the peripheral tumor cells." (PMID 30550540, 2018). "Tumors from STMN1 and control models were examined for markers of tumor cell proliferation (Ki67), keratin 17 and stathmin." (PMID 28977901, 2017). "In this study, expression of KRT17 was upregulated, especially in two tumour tissues (2D and 25D) of paired tumour-normal samples S2 and S25, respectively, detected to have this fusion." (PMID 28886030, 2017). "KRT17, which is an inductive keratin in the regenerative epithelium, acts in OSCC as a pathogenic keratin that facilitates tumor growth through stimulation of multiple signaling pathways." (PMID 27512993, 2016). "Since Amhr2-Cre is also expressed in the ovarian surface epithelium, immunofluorescence was performed using antibodies against epithelial cell markers, cytokeratin 8 (KRT8) and 17/19 (KRT17/19), to exclude the epithelial cell identity of the neoplasms." (PMID 27344183, 2016). "In our study, we demonstrated increased KRT17 expression in laryngocarcinoma tissues compared to non-tumor tissues by proteomic profiling, and confirmed this trend by western blot and RT-PCR." (PMID 25874882, 2015). "To further document the proliferative properties of these BCCs, we immunostained tumor tissue with an antibody specific for keratin-17, an outer root sheath marker protein." (PMID 26413810, 2015). "Verification studies using qRT-PCR, immunoblot and IHC assays confirmed that the expressions of S100A2, POSTN, FN1 and KRT17 were, indeed, significantly increased in tumor tissues." (PMID 25874882, 2015). "Hyperactivation of Rac1 in SCC tissues correlates with keratin 17 overexpression Treatment of DMBA/TPA results in tumor development and is accompanied by the induction of protumorigenic inflammation, which augments Wnt/β-catenin signaling." (PMID 24962779, 2014). "Keratin 17 expression correlates with tumor progression and poor prognosis in many cancers such as gastric adenocarcinoma and ovarian cancer." (PMID 24962779, 2014). "Historically, it was believed that BCCs arise from the lower PSU owing to the morphological resemblance of the tumour cells to hair follicles and the expression of hair follicle markers such as Krt17 and Krt19 in tumour tissues." (PMID 24961797, 2014).
tumor (continued). "In the current study, we demonstrated up-regulation of several matrix metalloproteinases (MMPs); and KRT17 in the tumor of almost all the tissue pairs." (PMID 24321518, 2013). "At this stage, our hypothesis was that the Intermediate cluster with the predominant expression of KRT17 represented the missing link in a continuum between the classical and basal tumor cell phenotypes." (PMID 39935174, 2025). "Microscopic sections of peritumor tissue show that the mucosal epithelium expresses KRT17, which may indicate damage or the initial stage of oncotransformation of cells located near the tumor site." (PMID 38540309, 2024). "Furthermore, IHC examination of the tissue showed that KRT13 expression indeed almost completely disappears in mucosal epithelial cells in tumor tissue biopsy specimens, and all cancer cells have a KRT17+ phenotype." (PMID 38540309, 2024). "In addition, high expression of keratin 17 has been correlated with tumor size, depth of invasion, and metastasis in gastric cancer." (PMID 39194725, 2024). "Interestingly, our data also suggest that premalignant mucosa reflects the tumor’s KRT17 expression pattern, with a much stronger abundance of this marker compared to normal mucosa." (PMID 39358322, 2024). "KRT17 mRNA was positively correlated with the size of the tumor (r = 0.204, p = 0.001)." (PMID 38979664, 2024). "Further, muscle markers TPM1/ACTA1 and the recently described HNSCC differentiation marker KRT17 correlate in the cell cultures and the original tumor tissue, indicating that our differentiation model faithfully reflects the differentiation behavior in human tumors." (PMID 39030166, 2024). "This indicates that KRT17 is a tumor-specific differentiation marker." (PMID 39358322, 2024). "The miR-18a/low tumours had higher expression of the luminality-associated genes like ESR1, GATA3, FOXA1, XBP1 and TFF1 and a lower expression of the basality-associated genes such as KRT18, KRT17, FOXC1, ANLN, STIL and MIA (p < 0.05)." (PMID 38786043, 2024). "Meanwhile, KRT17 played a role in DNA damage response and tumor initiation." (PMID 38979664, 2024). "The process of the GBC-neutrophil contact and subsequent oxLDL uptake may involve much more sophisticated mechanism beyond tumor-expressed KRT17 and neutrophil OLR1 activation, which require future exploration." (PMID 38822440, 2024). "Recent studies have revealed that KRT17 can inhibit tumor cell proliferation, migration and invasion in malignant tumors by regulating the Akt/mTOR pathway, glucose uptake, Wnt signaling pathway, epithelial-mesenchymal transition (EMT) and mTOR/S6K1 signaling pathway." (PMID 36765563, 2023). "We also found that HPV infection, the estrogen signaling pathway, cadherin binding, and intermediate cytoskeleton filament formation may affect KRT17-mediated tumor pathogenesis and development." (PMID 35646078, 2022). "Additionally, in vivo xenograft tumor studies inferred that knockdown of KRT17 clearly repressed tumorigenesis, i.e., lower tumor volume and weight, and Ki-67 level." (PMID 36248412, 2022). "Considering that KRT17 may play different roles in the development of tumor diseases, how it affects the survival and mechanism of the disease still needs to be further explored." (PMID 35646078, 2022). "In addition, we need to study KRT17 in human tumour tissues to understand the relationship between KRT17 and clinicopathological parameters." (PMID 35281081, 2022). "Therefore, further experiments are needed to verify how HER2 influences KRT17 expression, the specific effects of KRT17 on tumor progression, and the relationship between KRT17 and the tumor immune response." (PMID 36139022, 2022). "Hence, the upstream and downstream regulatory pathways of KRT17 are of significance, but further validation is needed, especially in unreported tumours or more precise mechanism studies." (PMID 35281081, 2022).
tumor (continued). "This suggests that the mechanism of action of KRT17 in malignant tumors is complex and diverse, that there may be multiple mechanisms in one tumor, and that multiple tumors may share similar mechanisms." (PMID 35646078, 2022). "In addition, KRT17 knockout or silencing can inhibit the growth of various tumour cell lines in vitro and in vivo." (PMID 35281081, 2022). "KRT17 plays a role with CD8+T cells, Tregs and cancer-related broblasts in malignant tumors, KRT17 and immune cells are involved in the formation and development of tumours, However, The specific mechanism of action is still unbelievable and needs further study." (PMID 35281081, 2022). "Another study showed that KRT17 was associated with histological grade and tumour invasion, but not with lymph node metastasis and tumour size." (PMID 35281081, 2022). "Moreover, the effect of human papillomavirus (HPV) on KRT17 was minimal when combining analysis of tumours with high KRT17 expression and an HPV-negative status." (PMID 35281081, 2022). "Furthermore, KRT17 knockout can also inhibit tumour cell proliferation, migration and invasion through the mTOR/S6K1 signaling pathway." (PMID 35281081, 2022). "In addition, the expression of KRT17 protein in metastatic lymph nodes was consistent with that in the primary tumour when KRT17 protein was detected." (PMID 35281081, 2022). "KRT17 can affect cell cycle and cell growth to influence tumor progression." (PMID 36139022, 2022). "KRT17 is highly expressed in several types of cancer with poor survival rates; therefore, KRT17 knockdown could suppress tumor proliferation, migration and invasion." (PMID 36139022, 2022). "Furthermore, the high expression of KRT17 can promote tumour growth by promoting cell migration and proliferation and inhibiting apoptosis and cell cycle arrest." (PMID 35281081, 2022). "Besides, we approved that knockdown of KRT17 extraordinarily restrained the xenograft tumor growth in vivo." (PMID 36248412, 2022). "In addition, amplification was the main type of KRT17 tumor variation, with an amplification rate of about 9%, followed by mutation, with a mutation rate of 4%." (PMID 35646078, 2022). "Functional characterization of Keratin 17 in various tumours." (PMID 35281081, 2022). "Genomic and proteomic studies suggest that KRT17 is highly expressed in most malignant tumor tissues or cells, and this high expression is related to tumour growth, metastasis and prognosis." (PMID 35281081, 2022). "Using data retrieved from our previous study, we demonstrated that the gene expression level of KRT13 was significantly down-regulated in OSCCs compared to their corresponding non-tumor epithelia, while the expression levels of KRT17, MKI67, and LAMC2 in OSCCs were significantly upregulated." (PMID 35524231, 2022). "Importantly, further analysis based on clinicopathological grade of the 91 OSCC tumor tissues revealed that the KRT17 protein expression level was significantly higher in tumors at stage III/IV than those at stage I/II." (PMID 35706019, 2022). "In addition, epithelial cell differentiation regulation-related genes, such as AKR1B1, SPRR1B, and keratin genes KRT6A, KRT19, and KRT17 were also highly expressed in mixed-lineage tumor cells." (PMID 35962452, 2022). "In addition, from the TCGA database, we also found that the high expression of KRT17 was correlated with the regional lymph node (N) stage of the tumor." (PMID 34935584, 2021). "In the present study, we found that KRT17 was closely related to these functions in tumor cells." (PMID 34935584, 2021). "Moreover, we also found that the expression of KRT17 was increased in HCC tumours with the lymph node metastasis." (PMID 32537856, 2020). "Furthermore, keratin 17 promotes epithelial proliferation and tumor growth in skin, and the downregulation of keratin 17 also attenuates hyperplasia and inflammation." (PMID 32664608, 2020).
tumor (continued). "We also found an increased expression of the prognostic marker KERATIN 17 in the L1low tumours." (PMID 32291413, 2020). "The 2 exceptions to this are KRT14 and KRT17, both of which are heavily up-regulated in the tumor." (PMID 33142242, 2020). "We have identified KRT17 expression in conventional RCCs as an independent negative survival factor indicating a higher risk for postoperative tumour relapse and cancer specific death of patients." (PMID 31602265, 2019). "In cancers arising from KRT17 negative single layered epithelia neo-expression of KRT17 has been associated with tumor progression." (PMID 31602265, 2019). "Collectively, these results indicate that KRT17 supports tumor growth in vivo." (PMID 27512993, 2016). "Keratin 17 was detected in nearly all GLI2A-expressing tumor cells." (PMID 26859571, 2016). "Indeed, we found that KRT17 promoted tumor growth by stimulating the Akt/mTOR pathway and glucose uptake." (PMID 27512993, 2016). "However, the relevance of KRT17 and tumor progression in laryngocarcinoma remains elusive, and the mechanisms involved still require further investigation." (PMID 25874882, 2015). "In tumor tissues of patients, Rac1 activation is positively correlated with keratin 17 expression." (PMID 24962779, 2014). "Besides, we found that RAS protein activator like 1 (RASAL1) and keratin 17 (KRT17) were clearly hypomethylated in the promoter region and over-expressed in the tumor samples compared to the controls." (PMID 22140553, 2011). "Increased expression of keratin 17 in endothelial cells may contribute to angiogenesis and may promote epithelial proliferation and tumor growth." (PMID 22140553, 2011). "Altogether, our findings support the hypothesis that platinum-caused DNA damage induces KRT17, which subsequently actively participates in changes in the cytoskeletal organization to enhance non-canonical epithelial differentiation, promoting tumor survival." (PMID 41399494, 2025). "A comparison of tumor and peritumor tissues showed that during oncotransformation in both studied groups, there were similar processes: the expression levels of keratins 4 and 13 were reduced, while the expression levels of keratin 17 and CD44 were significantly increased." (PMID 38540309, 2024). "However, KRT17 can discriminate the tumor recurrence after 12 months after surgery." (PMID 38514751, 2024). "In addition, KRT17 may have other pathways of action during the occurrence and development of human tumours, which still need to be studied and explored." (PMID 35281081, 2022). "In addition, univariate analysis showed that high pT stage, KRT17 expression, poor tumor differentiation, perineural invasion and lymphatic vascular invasion were poor prognostic factors, while multivariate analysis suggested that KRT17 expression was also an important prognostic factor." (PMID 35281081, 2022). "Similarly, KRT17 also shows the high expression levels in malignant tumour cell lines." (PMID 35281081, 2022). "However, KRT17 as a biomarker and therapeutic target for tumour prognosis remain a major challenge, as the exact molecular mechanisms of KRT17 action remain unclear." (PMID 35281081, 2022). "In addition, KRT17 can activate different macrophage populations and subtypes (such as M1 and M2) through interferon γ, tumor necrosis factor-α and interleukin 10, which play an important role in tumor proliferation and differentiation." (PMID 35646078, 2022). "Moreover, we found that KRT17 expression was also related to cytokine signaling pathways, indicating that KRT17 may affect the tumor immune response and thus affect patient survival." (PMID 36139022, 2022). "However, KRT17 is underexpressed in some tumors, and it is considered that KRT17 may play a role as a tumor suppressor gene in these tumors." (PMID 35281081, 2022). "Hence, KRT17 can be used as a potential prognostic biomarker for malignant tumours." (PMID 35281081, 2022).
tumor (continued). "Cell experiments suggest that KRT17 knockout could inhibit the proliferation and migration of GC cells, which may be achieved through the Akt/mTOR signalling pathway, and animal experiments also confirmed that KRT17 knockout could inhibit tumour growth." (PMID 35281081, 2022). "Additionally, ERBB2 and keratin 17 (KRT17) were found to locate in the same chromosome region, which might have the following tumor associations." (PMID 33133157, 2020). "Besides, Keratin 17 could promote epithelial proliferation and tumor growth by polarizing the immune response in skin mucosa." (PMID 25874882, 2015). "Research indicates that KRT17 expression is markedly increased in highly invasive OSCC cell lines and advanced-stage tumor samples, correlating with unfavorable patient prognoses." (PMID 40710326, 2025). "To further investigate KRT17 and SPRR3 as markers of HNSCC differentiation, we stained the original tumor tissue of P1 and P2 and HPV-negative tumor tissue of four additional patients with oropharyngeal and hypopharyngeal tumor location (P3-6)." (PMID 39358322, 2024). "In HNSCC and OSCC in other types of KRT (KRT17, KRT19), similarly to ours, increased protein levels were observed in the tumor compared to the healthy sample or surgical margin." (PMID 39000463, 2024). "The peaks of epithelial cells and tumor cells were notably enriched in the gene sets of ‘VIM, KRT5, KRT17’ and ‘KRT8, KRT18, FOXA1’, respectively." (PMID 38581422, 2024). "Pairwise analysis revealed that tumor tissues exhibited significantly elevated expression of KRT81, KRT6A, KRT17, and KRT14, which were positively correlated with FSTL3 expression, compared to that in normal tissues." (PMID 38240936, 2024). "Analyzing experimental data from two groups, both KRT17 and COL1A1 mRNA were highly expressed in case tissues, which are also correlated with age, blood glucose and tumor size." (PMID 38979664, 2024). "In our study, we confirmed a significant increase in KRT17 expression and a crucial decrease in KRT13 and KRT4 expression in tumor tissues relative to the peritumor region in all patients studied, regardless of tumor grade or patient smoking status." (PMID 38540309, 2024). "The differential expression between tumor and adjacent tissues expression levels displayed for KRT14, KRT16, KRT17, and KRT6B indicated that their expression levels were higher in normal tissues than in tumors." (PMID 36293530, 2022). "Another study also confirmed that KRT17 was up-regulated in ESCC tissues, which was correlated with age, tumour location, smoking, lymph node metastasis, T stage, N stage and TNM stage, but not with differentiation or vascular and nerve invasion." (PMID 35281081, 2022). "In vitro and in vivo experiments, the over-expression of KRT17 has been found to enhance the proliferation and migration of ESCC cells and promote tumour metastasis by activating medium-Akt signaling and inducing EMT." (PMID 35281081, 2022). "The differential gene expression levels between tumor and adjacent tissue displayed in the box plot showed that LAMB3, KRT14, KRT16, KRT17, and KRT6B expression levels were significantly (p < 0.001) higher in normal tissues than in tumors." (PMID 36293530, 2022). "Significantly elevated expression of KRT17 in highly invasive OSCC cell lines and advanced tumor specimens were observed and high KRT17 expression was correlated with poor overall survival." (PMID 35706019, 2022). "We combined the tumor expression data of TCGA and GTEx with the GEPIA2 tool to obtain the top 200 genes related to KRT17 expression." (PMID 35646078, 2022). "Among the total proteins, KRT17 expression was higher in COAD, LUAD, and UCEC than in normal tissues, while KRT17 expression was higher in BRCA and KIRC normal tissues than in tumor tissues." (PMID 35646078, 2022).